NPIPB15 (nuclear pore complex interacting protein family member B15)
Synonyms: NPIPL2; LOC440348; A-761H5.4
Tractability: Antibody: UniProt places it where antibodies can reach, with high confidence; UniProt predicts a signal peptide or a membrane-spanning region; its Gene Ontology location is reachable by antibodies, with medium confidence. PROTAC: ubiquitination databases record sites on it.
Gene: Protein-coding gene on chromosome 16 (74,376,306 to 74,392,115, forward strand). Ensembl gene ENSG00000196436.
Subcellular location: Secreted
Subcellular location (Human Protein Atlas): Nucleoplasm
Gene Ontology:
Cellular component: extracellular region
Genetic constraint (gnomAD): Loss-of-function variants: 5 observed, 16.4 expected, observed/expected ratio (o/e) 0.3, 90% interval 0.16 to 0.64. The synonymous counts are far from expectation, so gnomAD's model fits this gene poorly and the ratio says little. Missense variants: 98 observed, 253.46 expected, observed/expected ratio (o/e) 0.39, 90% interval 0.33 to 0.46. Synonymous variants: 42 observed, 86.21 expected, observed/expected ratio (o/e) 0.49, 90% interval 0.38 to 0.63.
Homologues: Paralogues in human: NPIPB7 (89% identical), NPIPB9 (86% identical), NPIPB6 (86% identical), NPIPB8 (86% identical), NPIPB13 (68% identical), NPIPB5 (68% identical), NPIPB12 (68% identical), NPIPB4 (68% identical), NPIPB11 (67% identical), NPIPB2 (61% identical), NPIPA7 (51% identical), NPIPA8 (51% identical), and 7 more.
Diseases named in the same sentence as NPIPB15 in open-access papers:
NPIPB15 is named in the same sentence as 4 diseases in open-access papers, as found by Europe PMC text mining. Sharing a sentence is not in itself a finding about the gene and the disease. The quoted sentences say what the papers report.
acute myeloid leukemia (1 paper, 2017). Acute myeloid leukemia (AML) is a group of neoplasms arising from precursor cells committed to the myeloid cell-line differentiation. "Interestingly, albeit no formerly known association with tumor, NPIPB15 I419T point mutation was unanimously detected in three cases, suggesting its variation could be a common event in Chordoma progression such as IDH1 in glioma and acute myeloid leukemia (AML)." (PMID 27901492, 2017).
tumor (3 papers, 2017 to 2022). "Our data also showed that the VAF of some primary or metastatic-specific SNVs in both tumour lesions was too low to be detected by SNV callers, such as SYTL1 and NPIPB15 in CRC1." (PMID 34507604, 2021).
NPIPB15 also shares sentences with these, for which no sentence is quoted: chordoma (1 paper); glioma (1).